SRCAP (Snf2 related CREBBP activator protein)
Diseases named in the same sentence as SRCAP in open-access papers (continued):
Sharing a sentence is not in itself a finding about the gene and the disease.
tumor (7 papers, 2019 to 2024). "Furthermore, we found co-mutation with MSH3 across the tumours underlying each model, ranging from 20% (SRCAP) to 33% (BMPR2) of the mutated tumours." (PMID 36883553, 2023). "The remaining tumor fraction comprises a heterogenous group characterized by genetic alterations leading to overexpression of HMGA1/HMGA2, inactivation of the SRCAP histone loading complex, or biallelic loss of fumarate hydratase." (PMID 39764110, 2024). "The deregulation of histone chaperone complexes can contribute to tumor development, and both chaperone complexes, SRCAP and p400–TIP60, are affected." (PMID 37958827, 2023). "Our results proves that miR-641 inhibits the translation of SRCAP by binding to its 3ʹUTR region, while high-level LINC00665 promotes SRCAP expression through the sponge adsorption of miR-641, thus promoting the proliferation and metastasis of tumor cells." (PMID 35152838, 2022). "Inactivating frameshift and nonsense mutations in SRCAP have been previously reported in HCC21, suggesting a tumor-suppressor function in HCC." (PMID 31796844, 2019). "Therefore, we predicted that SRCAP involved in the regulation of tumor cell proliferation and metastasis through the regulation of specific-genes’ transcription, which need further study." (PMID 35152838, 2022). "Finally, we confirmed in clinical samples that LINC00665 and SRCAP are highly expressed in tumor tissues, while miR-641 is low in tumor tissues." (PMID 35152838, 2022). "Similarly striking is that LoF of genes encoding SRCAP complex subunits was linked exclusively to ULs and, based on phenome-wide results across 15,500 phenotypes, had no clear associations to other neoplasia or disease." (PMID 36773604, 2023).
genetic disease (3 papers, 2016 to 2024). "SRCAP was first discovered as the binding partner of CREBBP (also known as CBP), and mutations in SRCAP cause a rare genetic disorder known as Floating–Harbor syndrome." (PMID 27240470, 2016).
infection (1 paper, 2024). The state of being infected such as from the introduction of a foreign agent such as serum, vaccine, antigenic substance or organism. "The knocking down of SRCAP could block TA-12 infection, downregulate HES1 and upregulate RBP-Jκ, which was consistent with those of the LY-411575, an inhibitor of Notch signaling." (PMID 39530666, 2024). "Several viruses have been reported to interact with SRCAP to regulate the infection." (PMID 39530666, 2024). "In both the lungs and hilar lymph nodes, infection with TA-12 could increase the level of SRCAP, whereas the addition of LY-411575 could reduce the viral load." (PMID 39530666, 2024).
neurodegenerative disease (1 paper, 2014). A disorder of the central nervous system characterized by gradual and progressive loss of neural tissue and neurologic function. "If SRCAP is indeed an ALS disease gene, this further underscores the potential link between neurodevelopmental and neurodegenerative diseases." (PMID 25299611, 2014).
SRCAP also shares sentences with these, for which no sentence is quoted: developmental delay (3 papers); glioma (3); Kabuki syndrome (3); neurodevelopmental disorder (3); growth deficiency (2); Phelan-McDermid syndrome (2); 3-M syndrome (1); acromelic dysplasia (1); Alagille syndrome (1); amyotrophic lateral sclerosis (1); Aortic Valve Disease 1 (1); autism (1); autoimmune disease (1); autoimmune encephalitis (1); basal cell nevus syndrome (1); bladder tumors (1); blepharocheilodontic syndrome (1); breast tumors (1); cerebellar ataxia (1); Cerebellofaciodental Syndrome (1); cerebral cavernous malformation (1); cleft lip (1); colitis (1); deafness (1); Developmental and epileptic encephalopathies (1); episodic ataxia (1); experimental autoimmune encephalomyelitis (1); glioblastoma (1); incontinentia pigmenti (1); Intellectual disability (1).
A further 25 diseases each share a sentence with SRCAP in 1 paper.